PHLDA2 (pleckstrin homology like domain family A member 2)
Diseases named in the same sentence as PHLDA2 in open-access papers (continued):
Sharing a sentence is not in itself a finding about the gene and the disease.
cancer (continued). "However, there was a strong positive correlation between the low level of PHLDA2 expression and high survival in these forms of cancer." (PMID 38921000, 2024). "Herein, we assessed whether PHLDA2 promotes cancer and chose to test this in CRC because it is an epithelial tumor." (PMID 32385195, 2020). "EMT partially contributed to PHLDA2-induced cancer metastasis." (PMID 32385195, 2020). "Silencing PHLDA2 reduces cancer cell aggressiveness and proliferation." (PMID 31105744, 2019). "Moreover, elevated expression of PHLDA2 is related to poor prognoses in several types of cancer, and PHLDA2 could upregulate SDC1 expression, which contributes to cancer cell aggressiveness." (PMID 36061148, 2022). "Our multiomics research showed that PHLDA1, PHLDA2, and PHLDA3 have various functions in the development of cancer and regulate the prognosis of patient’s cancer differently." (PMID 38921000, 2024). "Based on information from the PrognoScan database, the predictive significance of PHLDA1, PHLDA2, and PHLDA3 expression levels for various cancer patients was also evaluated." (PMID 38921000, 2024). "Using the cBioPortal, we independently analyzed the genetic changes in PHLDA1, PHLDA2, and PHLDA3 in distinct cancer types and then provided a comparative report regarding the functional protein partners of glutaminases obtained using PPI network analysis." (PMID 38921000, 2024). "Decreased PHLDA2 expression increases cell proliferation and reduces sensitivity to targeted agents in EGFR/ErbB2-driven cancer." (PMID 37575253, 2023). "In particular, the AKT-inhibitor molecules PHLDA1 and PHLDA2 are simultaneously upregulated by oncogenic ERK signaling and confer resistance to ERK pathway-targeted therapeutics on cancer cells." (PMID 35831322, 2022). "More important, this group of genes also included genes whose roles in cancer have yet to be fully addressed (e.g., TM4SF1, TM4SF19, EMP1, PHLDA1, and PHLDA2)." (PMID 35831322, 2022). "According to these findings, PHLDA1, PHLDA2, and PHLDA3 may partially co-express to control the prognosis of cancer." (PMID 38921000, 2024). "However, the proteasome inhibitors MG132 and bortezomib, which also provoke ER stress, significantly upregulated PHLDA1 and PHLDA2 protein and mRNA expression in HEK293 and in various cancer cells." (PMID 35831322, 2022). "In the present study, we focused on the strongly regulated novel gene by EGFR/ErbB2 blockade, PHLDA2 as it has not been investigated before as a target of oncogenic pathways in cancers." (PMID 29861842, 2018). "Better understanding of PHLDA2′s regulation and its interactions with membrane PIPs/inhibition of AKT activation can yield novel therapeutic options for the treatment of patients with EGFR/ErbB2-driven cancers." (PMID 29861842, 2018). "PHLDA2 may change the composition of ECM and promote cancer cells to acquire EMT characteristics." (PMID 38827322, 2024). "Thus, they function as cancer-promoting genes, such as FOXQ1, PHLDA2, LPCAT2, AP1S3, and EPS8." (PMID 32977589, 2020). "Indeed, PHLDA2 overexpression suppresses anchorage-independent cell growth and decreased PHLDA2 expression results in increased cell proliferation and reduced sensitivity to targeted agents of EGFR/ErbB2-driven cancers demonstrating functional relevance for this interaction." (PMID 29861842, 2018). "In conclusion, we show PHLDA2 regulation by EGFR/ErbB2 signaling, demonstrate a correlation between PHLDA2 expression, AKT pathway activation and EGFR mutational status and show that PHLDA2 has key negative feedback inhibitory functions in EGFR/ErbB2-driven cancer cells." (PMID 29861842, 2018).
metabolic disease (1 paper, 2019). A congenital disorder (due to inherited enzyme abnormality) or acquired (due to failure of a metabolically important organ) disorder resulting from an abnormal metabolic process. "Placental CDKN1C, PHLDA2 and IGF-2 levels monitoring may be useful for prediction and prevention of the development of SGA births and its related postnatal metabolic diseases." (PMID 31194812, 2019).
PHLDA2 also shares sentences with these, for which no sentence is quoted: hydatidiform mole (2 papers); neuroblastoma (2); triple-negative breast carcinoma (2); acute myeloid leukemia (1); alcohol dependence (1); asphyxia (1); bacterial infection (1); benign bone tumors (1); bone tumor (1); breast tumor (1); clear cell renal cell carcinoma (1); embryonic carcinoma (1); endometrial cancer (1); gestational diabetes (1); Hypercalcemia (1); infection (1); lymphoma (1); non-small cell lung carcinoma (1); osteoarthritis (1); prostate carcinoma (1); renal fibrosis (1); soft tissue tumors (1); Wilms tumor (1).